PDE12 (phosphodiesterase 12)
Description:
Enzyme that cleaves 2',5'-phosphodiester bond linking adenosines of the 5'-triphosphorylated oligoadenylates, triphosphorylated oligoadenylates referred as 2-5A modulates the 2-5A system. Degrades triphosphorylated 2-5A to produce AMP and ATP. Also cleaves 3',5'-phosphodiester bond of oligoadenylates. Plays a role as a negative regulator of the 2-5A system that is one of the major pathways for antiviral and antitumor functions induced by interferons (IFNs). Suppression of this enzyme increases cellular 2-5A levels and decreases viral replication in cultured small-airway epithelial cells and Hela cells.
Synonyms: 2'-PDE; 2-PDE; DKFZp667B1218; 3635; ARF4-AS1
Tractability: Small molecule: a structure with a bound ligand is known. PROTAC: ubiquitination databases record sites on it; its protein half-life has been measured; a small molecule that binds it is known.
Target class: Enzyme; Hydrolase
Gene: Protein-coding gene on chromosome 3 (57,556,274 to 57,656,480, forward strand). Ensembl gene ENSG00000174840.
Subcellular location: Mitochondrion matrix
Pathways (Reactome):
Immune System: OAS antiviral response
Gene Ontology:
Molecular function: 3'-5'-RNA exonuclease activity; exonuclease activity; poly(A)-specific ribonuclease activity; catalytic activity
Biological process: antiviral innate immune response; cellular response to dsRNA; cellular response to interferon-alpha; cellular response to type II interferon; mitochondrial mRNA catabolic process; nuclear-transcribed mRNA catabolic process, deadenylation-dependent decay; nucleic acid metabolic process; positive regulation of viral genome replication; regulation of mitochondrial mRNA stability; defense response to virus
Cellular component: mitochondrial matrix; mitochondrion; cytosol
Genetic constraint (gnomAD): Loss-of-function variants: 26 observed, 47.68 expected, observed/expected ratio (o/e) 0.55, 90% interval 0.4 to 0.76. The synonymous counts are far from expectation, so gnomAD's model fits this gene poorly and the ratio says little. Missense variants: 668 observed, 841.88 expected, observed/expected ratio (o/e) 0.79, 90% interval 0.74 to 0.85. Synonymous variants: 283 observed, 348.81 expected, observed/expected ratio (o/e) 0.81, 90% interval 0.74 to 0.89.
Homologues: Orthologues: chimpanzee PDE12 (99% identical), macaque PDE12 (99% identical), dog PDE12 (93% identical), rabbit PDE12 (93% identical), pig PDE12 (93% identical), guinea pig PDE12 (90% identical), mouse Pde12 (88% identical), rat Pde12 (85% identical), zebrafish pde12 (55% identical), tropical clawed frog pde12 (53% identical), Drosophila melanogaster CG31759 (32% identical), Caenorhabditis elegans pde-12 (22% identical). Paralogues in human: CNOT6L (20% identical), CNOT6 (20% identical), NOCT (20% identical), ANGEL1 (19% identical), ANGEL2 (17% identical).
Diseases named in the same sentence as PDE12 in open-access papers:
PDE12 is named in the same sentence as 12 diseases in open-access papers, as found by Europe PMC text mining. Sharing a sentence is not in itself a finding about the gene and the disease. The quoted sentences say what the papers report.
viral infection (5 papers, 2015 to 2023). "One such enzyme is phosphodiesterase 12 (PDE12) which degrades 2-5A and thus inhibition/decreased levels of PDE12 might up-regulate viral-infection-induced OAS/RNase-L pathway resulting in increased resistance to viral pathogens." (PMID 32325933, 2020). "Despite PDE12, ENPP1 and AKAP7 degrades 2′-5′ oligoadenylates in vitro their importance during viral infection, has yet to be reported." (PMID 26113370, 2015). "Inhibition of PDE12 may up-regulate the 2’,5’-Oligoadenylate synthetase (OAS) enzymes and RNase-L(OAS/RNase-L) pathway in response to viral infection resulting in increased resistance to a variety of viral pathogens." (PMID 35058920, 2021). "The most down-modulated genes were related to T helper 2 pathway activation and induction of FOXP3 expression (AREG), immune tolerance (SMAD6), response to bacterial and viral infection and inflammation (CXCL8, PDE12, STX19, DFNB31), cell transport of glucose and organelles (KIF5A, SCL2A7)." (PMID 35058920, 2021).
COVID-19 (2 papers, 2022 to 2023). A disease caused by infection with severe acute respiratory syndrome coronavirus 2. "Among them, three (RPS28, RPLP2, and PDE12) had matching risk factor genes showing consistent patterns, i.e., transcriptional upregulations increased the COVID-19 mortality risk." (PMID 35547187, 2022).
gastric cancer (1 paper, 2022). A primary or metastatic malignant neoplasm involving the stomach. "Few studies have focused on the biological functions of PRICKLE2, PDE12, RBP1, THSD7B, and TUBB6 in gastric cancer." (PMID 36226177, 2022).
glioblastoma (1 paper, 2022). The most malignant astrocytic tumor (WHO grade IV). "Among these proteins, we found 2,5-phosphodiesterase 12 (Pde12) a negative regulator for antiviral and antitumor functions induced by interferons and Eukaryotic translation initiation factor 3 subunit E (Eif3e) which is essential for proliferation and survival of glioblastoma cells." (PMID 33402730, 2022).
type 2 diabetes (1 paper, 2022). "We analyzed PDE12 expression in islets from non-diabetic donors, individuals with newly (median disease duration 35 days) and recently (5 years) diagnosed T1D, and individuals with type 2 diabetes (T2D)." (PMID 36307540, 2022). "However, PDE12 expression was not altered in individuals with type 2 diabetes (median disease duration, 2.0 years)." (PMID 36307540, 2022).
mitochondrial disease (2 papers, 2025). "Variants in the PDE12 gene can cause a mitochondrial disease that begins in infancy and results in combined deficiencies in the OXPHOS system." (PMID 39567835, 2025). "Pathogenic missense variants in the PDE12 gene cause neonatal-onset mitochondrial disease resulting in neurological and muscular disorders." (PMID 39567835, 2025). "In conclusion, the discovery of pathogenic variants in PDE12 expands the list of nuclear-encoded mitochondrial proteins that cause primary mitochondrial diseases (PMDs)." (PMID 39567836, 2025). "In this study, we show that rare PDE12 variants may cause an early-onset mitochondrial disease presentation, with the first symptoms observed during development in utero." (PMID 39567835, 2025). "In this present work, we report the identification of rare, damaging missense variants in the PDE12 gene (NM_177966.7) in four individuals from three unrelated families, including two foetal siblings, who presented with severe, early-onset mitochondrial disease." (PMID 39567835, 2025).
infection (1 paper, 2022). The state of being infected such as from the introduction of a foreign agent such as serum, vaccine, antigenic substance or organism. "PDE12-null cells were also resistant to infection with encephalomyocarditis virus, human rhinovirus and respiratory syncytial virus, highlighting a protective effect that is associated with decreased PDE12 activity and thereby increased RNaseL activity." (PMID 36307540, 2022).
tumor (1 paper, 2022). "The decreased level of PDE12 indicated the poor prognosis of GC patients, and we observed weaker PDE12 staining in tumor tissue." (PMID 36226177, 2022).
PDE12 also shares sentences with these, for which no sentence is quoted: colorectal cancer (1 paper); diabetes (1); lactic acidosis (1); lung adenocarcinoma (1).